ALK (ALK receptor tyrosine kinase)
Diseases named in the same sentence as ALK in open-access papers (continued):
Sharing a sentence is not in itself a finding about the gene and the disease.
neuroblastoma (continued). "Here, the authors use circulating tumour DNA, collected as part of a phase I trial investigating lorlatinib (ALK inhibitor) in pediatric patients with ALK-driven neuroblastoma, to detect early resistance mechanisms." (PMID 37147298, 2023). "Here, we report the results of prospective serial ctDNA analysis from patients with relapsed or refractory ALK-driven neuroblastoma who received lorlatinib therapy." (PMID 37147298, 2023). "In contrast to the oncogenic ALK-F1174S mutation that has been reported to be activating in the context of full-length ALK in neuroblastoma, EML4-ALK (F1174S) variant 1 exhibits impaired kinase activity leading to loss of oncogenicity." (PMID 38264745, 2023). "Despite signalling to kinases implicated in major metabolic pathways, there is a paucity of information linking ALK to the regulation of cancer metabolism and, by extension, neuroblastoma." (PMID 37414143, 2023). "ALK alterations were assessed in neuroblastomas at diagnosis and/or relapse from a total of 943 patients, covering all stages of disease." (PMID 36807339, 2023). "Among targeted therapies proposed for neuroblastoma treatment, ALK inhibitors have come furthest in clinical application." (PMID 35362827, 2022). "Because ALK fusion protein is mainly expressed inside the cell, CAR-T therapy targeting ALK is currently mainly tested in neuroblastoma." (PMID 35958559, 2022). "The activating mutations in the anaplastic lymphoma kinase gene (ALK) play important roles in familial and sporadic neuroblastoma." (PMID 35681734, 2022). "Our data suggest that the combinational application of ALK and p110α inhibitors is worth testing to treat ALK-positive neuroblastoma." (PMID 36585695, 2022). "It has been found that T cells expressing a CAR incorporating the single-chain variable fragment against the ALK extracellular domain lyse ALK-positive neuroblastoma cell lines." (PMID 35958559, 2022). "For neuroblastoma with ALK mutations, the TITAN study (transatlantic integration targeting ALK in neuroblastoma) will investigate the frontline addition of lorlatinib, an ALK inhibitor with activity against a wider range of ALK mutations and penetrance to CNS." (PMID 35362827, 2022). "The roles of ALK in neuroblastoma pathogenesis have been extensively characterized, with several reviews published in recent years." (PMID 34716856, 2022). "Here we investigated anaplastic lymphoma kinase (ALK) inhibitor resistance in neuroblastoma, a childhood cancer frequently affected by activating ALK alterations." (PMID 35689207, 2022). "Mechanistically, inhibition of p110α decreased anaplastic lymphoma kinase (ALK) in neuroblastoma cells by decreasing its protein stability." (PMID 36585695, 2022). "Clinical experience with ALK inhibition in neuroblastoma has hitherto mainly been collected in patients with refractory or relapsed tumors." (PMID 35362827, 2022). "As ALK expression is restricted in normal tissue and over‐expressed in neuroblastoma, it is an ideal target for cancer treatment." (PMID 36029175, 2022). "Germline mutations of anaplastic lymphoma kinase (ALK) and paired-like homeobox 2B (PHOX2B) genes are pivotal predisposition factors in hereditary neuroblastoma." (PMID 35454815, 2022). "In contrast, phosphorylation of these sites was significantly increased in HEK 293 cells with doxycycline-induced ALK overexpression and in ALK-active neuroblastoma NB-1 and/or KP-N-RT-BM-1 cells." (PMID 35508387, 2022). "N-MYC proto-oncogene protein (MYCN) and Anaplastic Lymphoma Kinase (ALK) are the two important oncogenic drivers of neuroblastoma." (PMID 36585695, 2022). "Here, we analyzed ALK inhibitor resistance in neuroblastoma, and demonstrated that loss of NF1 or mutation of NRASQ61K can lead to ALK inhibitor resistance." (PMID 35689207, 2022). "Once more, the fact that some of such RTKs have previously been described as important players in neuroblastoma tumor biology (e.g., ALK, KIT, MET, and RET) again validates this approach." (PMID 34716856, 2022).
neuroblastoma (continued). "In our comparison between two neuroblastoma cell lines representatives of ALK-driven and MYCN-amplified disease, there is clearly heterogeneity of response to ASCL1 knockout despite similar initial expression levels." (PMID 36263020, 2022). "Recently, potentially pathogenic germline variants of ALK, CHEK2, PINK1 and BARD1 genes were discovered in high-risk neuroblastoma, including the ALK p.Arg1275Gln variant, which is frequently seen in familial neuroblastoma." (PMID 35454815, 2022). "ALK, the second most common driver in neuroblastoma after MYCN, is a receptor tyrosine kinase which in the neuroblastoma context first attracted attention in conjunction with the rare hereditary neuroblastomas." (PMID 35362827, 2022). "Only the ALK inhibitor ceritinib, improved the response rate (2 of 7) of the neuroblastoma INF_R_359_r3 zPDX model." (PMID 35159116, 2022). "In a proof-of-concept study, a novel ALK targeting antibody–drug conjugate showed efficacy in preclinical neuroblastoma models." (PMID 36337169, 2022). "Recent data from genetically engineered mouse models of neuroblastoma confirm that ALK and MYCN cooperate to promote tumorigenesis." (PMID 34716856, 2022). "The oncogenic mechanism in neuroblastoma operates by activation of RAS-MAPK-ERK and other downstream pathways, and can be initiated by activating mutations of ALK, ALK amplifications, or, possibly, changes to the ALK ligands ALKAL1 and ALKAL2." (PMID 35362827, 2022). "When deregulated, ALK also has high oncogenic potential, and aberrant ALK activation has been described in many different malignancies, including neuroblastoma." (PMID 36140661, 2022). "Our results suggest MEK inhibitor sensitivity is a new vulnerability and collateral sensitivity in a subset of ALK inhibitor-resistant neuroblastomas." (PMID 35689207, 2022). "Flotillin-1 has been reported to interact with ALK and regulate its lysosomal degradation through endocytosis in neuroblastoma cells." (PMID 35508387, 2022). "Somatic mutational burden increases in relapsed neuroblastoma and an increased frequency of mutations in genes involved in the RAS‐MAPK pathway, including the oncogene ALK, has been reported at relapse." (PMID 36029175, 2022). "We used the neuroblastoma cell lines SH-SY5Y (ALKF1174L) and LAN-5 (ALKR1275Q, MYCN-amplified), to represent ALK-mutated neuroblastoma within a genomic background either with or without MYCN amplification." (PMID 35689207, 2022). "Preclinical in vivo data involving anti-ALK (anaplastic lymphoma kinase) CAR for the targeting of neuroblastoma models appear to be promising in terms of immunomodulation and tumor shrinkage." (PMID 36031601, 2022). "Genes with the highest priority for potential targeted therapy are highlighted, e.g. ALK in neuroblastoma and RAS in acute lymphoblastic leukaemia." (PMID 36182817, 2022). "Several molecular biomarkers associated with the occurrence and progression of neuroblastoma have been reported, including MYCN, a clinically recognized oncogenic transcription factor-related biomarker, anaplastic lymphoma kinase (ALK), and PHOX2B." (PMID 36237324, 2022). "ALK (Anaplastic lymphoma kinase) is a receptor tyrosine kinase that plays a role with N-Myc in the pathogenesis of neuroblastoma and other malignancies, including those of the prostate." (PMID 36358740, 2022). "In a PDX model of pediatric neuroblastoma harboring mutations of anaplastic lymphoma kinase (ALK), CDK-i synergized with the ALK inhibitor, Ceritinib, inducing cell-cycle arrest and cell death." (PMID 35712501, 2022).
neuroblastoma (continued). "In July 2016, the clinical trial called Next Generation Personalized Neuroblastoma Therapy (NEPENTHE) was initiated: it had been enrolling patients between 1-21 years old with a refractory or relapsed neuroblastoma with alterations of the ALK gene." (PMID 36295546, 2022). "Here, we have investigated the role of ASCL1 in maintaining proliferation and controlling differentiation in both MYCN amplified and Anaplastic Lymphoma Kinase (ALK)-driven neuroblastoma cells." (PMID 36263020, 2022). "Structural genomic changes found in subsets of neuroblastoma, and linked to tumorigenesis and reduced survival, include MYCN amplification, ALK activating mutations, 1p36 deletion, or 17q gain." (PMID 34716856, 2022). "Germline variants of ALK and PHOX2B are strongly associated with familial predisposition to neuroblastoma, the latter also associated with congenital central hypoventilation syndrome and Hirschsprung disease." (PMID 35768791, 2022). "The first clinical trial of the lead substance crizotinib (NCT00939770) started shortly after ALK was discovered as an oncogenic driver in neuroblastoma." (PMID 35362827, 2022). "For example, the expression footprint of six neuroblastoma-related genes (ALK, BIRC5, CCND1, MYCN, NTRK1 and PHOX2B) have been used to differentiate neuroblastoma molecular subtypes." (PMID 34842635, 2021). "Similar findings were observed in neuroblastoma driven by the expression of the ALK and MYCN genes with lorlatinib and crizotinib, respectively." (PMID 34063424, 2021). "Here, we describe pathological activation of ALK in the neural crest, which promotes proliferation and migration, while preventing differentiation, thus inducing the onset of neuroblastoma." (PMID 34769149, 2021). "This was given emphasis when Siaw and colleagues proposed that ALK activation in neuroblastoma can inhibit DLG2 transcription via ERK1/2 and specificity protein 1 (SP1) signalling, thus impairing DLG2-induced differentiation." (PMID 34769149, 2021). "Lately, these methods have been coupled with strategies targeting specific oncogenic drivers of neuroblastoma, including MYCN, ALK, and TrkB, that are associated with HR-NB, and novel treatment strategies are currently being investigated." (PMID 34204830, 2021). "PDX models of ALK mutant neuroblastoma have been pivotal in recommending particular ALK targeting small molecules for clinical studies." (PMID 33808071, 2021). "Evidence linking pathological activation of ALK with neuroblastoma cell migration has been limited; nevertheless, there have been a sprinkling of papers." (PMID 34769149, 2021). "Experimental results in transgenic mouse models have identified activating ALK mutations and MYCN overexpression as the main oncogenic drivers of neuroblastoma." (PMID 34638328, 2021). "A third-generation inhibitor, lorlatinib, remains active against a broad range of known ALK mutations in preclinical models of EML4-ALK+ NSCLC and neuroblastoma." (PMID 33466277, 2021). "Overexpression of ALK mutants or fusions results in increased migration and invasiveness in neuroblastoma cells via upregulation of the MAPK pathway target ETV5." (PMID 34769149, 2021). "Previous studies found that ALK extracellular cleavage exists in the developing brain of rats and ALK-expressing cancer neuroblastoma." (PMID 33947097, 2021). "The role of c-MYC in ALK inhibitor resistance has been identified in some tumor types (glioblastoma, neuroblastoma, etc.)." (PMID 34063424, 2021). "Further mechanistic investigation taking this information into account should extend our understanding of the importance of ALKAL ligands for ALK activity and signaling in a neuroblastoma context." (PMID 34885007, 2021). "Sparse information is available for additional, rarer ALK+ tumors like neuroblastoma, colon, prostate, thyroid, IMT." (PMID 34680298, 2021). "ALK rearrangements are found in 23% of investigated neuroblastoma cell lines and a subset of neuroblastoma tumours." (PMID 34769149, 2021).
neuroblastoma (continued). "(2002) described ALK amplification in the NB-39-nu neuroblastoma cell line, which leads to constitutive activation of ALK." (PMID 34769149, 2021). "The ALK gene codes for a tyrosine kinase and is found not only in neuroblastoma but also in lung malignancies and lymphomas." (PMID 34842635, 2021). "In fact, through mutation, ALK activation uncoupled from ligand binding may result in a blockage of differentiation, leading to the hypothesis that ectopic ALK signalling acts very early in the neural crest differentiation programme when initiating neuroblastoma." (PMID 34769149, 2021). "Understanding the effects of ALK activity on neural crest cells will help find new targets for neuroblastoma treatment." (PMID 34769149, 2021). "Further targets in high-risk neuroblastoma include the telomerase reverse transcriptase (TERT) and the oncogene ALK." (PMID 35008547, 2021). "Currently, we are using a variety of human disease and animal models to establish the role of ALK in development and neuroblastoma initiation." (PMID 34769149, 2021). "For this reason, mutations in RAS and RAS-related pathways are usually assessed by a panel of genes including anaplastic lymphoma kinase (ALK), which is mutated in familial and sporadic neuroblastomas." (PMID 34069817, 2021). "Accordingly, pharmacological inhibitors of Trk and ALK RTKs are being tested in clinical trials in neuroblastoma." (PMID 34957126, 2021). "In neuroblastoma (NBL), amplifications and point mutations in the anaplastic lymphoma kinase (ALK) gene correlate with an adverse prognosis." (PMID 34575503, 2021). "ALK TKIs have been evaluated in ALK-driven neuroblastoma cell lines, mouse models, and ongoing clinical trials." (PMID 34591871, 2021). "In this review, we will summarise the current understanding of ALK function and consider its potential role in neural crest development and in the onset of neuroblastoma tumorigenesis." (PMID 34769149, 2021). "Indeed, using chicken embryo grafting experiments, Delloye-Bourgeois and colleagues were able to show that neuroblastoma cells carrying ALK gain-of-function mutations could follow the neural crest migratory paths, but did continue to proliferate and form tumour-like masses." (PMID 34769149, 2021). "In summary, our current study provides evidence for the potential of pyrrole-imidazole polyamide ALK inhibitor CCC-003 for the treatment of neuroblastoma thus offering a possible solution to the problem of tyrosine kinase inhibitor resistance." (PMID 34591871, 2021). "The Felix neuroblastoma PDX harbours the third most common ALK mutation found in neuroblastoma, and it exhibits de novo resistance to the first generation ALK inhibitor, crizotinib, which mirrors that seen clinically for this subgroup of patients." (PMID 33808071, 2021). "Neoplasms such as anaplastic large-cell lymphoma, inflammatory myofibroblastic tumours, non-small-cell lung cancer (NSCLC), and neuroblastoma have rearrangements within the oncogenic ALK gene." (PMID 34769519, 2021). "MYCN and ALK copy number was assessed in cfDNA samples from 16 patients with active neuroblastoma (14 at initial presentation and 2 at metastatic recurrence) and 3 patients in remission." (PMID 34282791, 2021). "PTPRZ1 substrates with potential relevance in neuroblastoma include ALK, TrkA, p190 RhoGAP, β-catenin, and SFK, among others." (PMID 34957126, 2021). "To overcome the issue of ALK inhibitor resistance in neuroblastoma, we used a novel PI polyamide designed to target the mutant ALK gene in a manner different from that of ATP-competitive inhibitors." (PMID 34591871, 2021). "These tumors exhibited a RNA expression signature similar to that of ALK mutant/MYCN driven neuroblastoma." (PMID 34885007, 2021). "One such tumor is neuroblastoma, which is characterized by a variety of driver events, including MYCN amplification and ALK mutations." (PMID 33718380, 2021).
neuroblastoma (continued). "They showed that Ibrutinib treatment can effectively inhibit the growth of neuroblastoma xenograft in nude mice, and the combination of ibrutinib and the ALK inhibitor crizotinib further enhanced the inhibition." (PMID 34164404, 2021). "Mutations of anaplastic lymphoma kinase (ALK), present in 8% of all patients at diagnosis, are the most common mutations activating the RAS/MAPK pathway in neuroblastoma." (PMID 34735429, 2021). "In the present study, CCC-003 had a 10-fold lower IC50 value compared to these two inhibitors, suggesting that it is more cytotoxic in neuroblastoma cells than other ALK inhibitors." (PMID 34591871, 2021). "ALK amplification has also been reported in neuroblastoma almost invariably together with amplification of the adjacent gene MYCN, with possible synergistic effects in driving cell growth and survival." (PMID 34063424, 2021). "In neuroblastoma (NB), the ALK receptor tyrosine kinase can be constitutively activated through activating point mutations or genomic amplification." (PMID 34115544, 2021). "ALK is the first directly targetable tyrosine kinase to be identified as a driver oncogene in neuroblastoma." (PMID 33808071, 2021). "Using neuroblastoma cell lines, we show that ALK modulates RET signaling at the level of RET phosphorylation, as well as at the level of transcription." (PMID 33921066, 2021). "Another drug, entrectinib, is a multi-targeted RTK inhibitor with action not only against ALK but also the TRK-B receptor, which is expressed in over half of high-risk neuroblastoma tumors and associated with a poor prognosis." (PMID 34298746, 2021). "This makes RAS/MAPK pathway inhibition a promising treatment option for neuroblastoma, and ALK and MEK inhibitors are already being tested in early clinical trials." (PMID 34735429, 2021). "Non-silent SNVs (2–6 per tumour) in cancer-related genes (HRAS, ALK and ATM) occurred exclusively in high-risk neuroblastomas and were clonal in a subset of patients but also spatially or temporally heterogeneous in others." (PMID 34815394, 2021). "To gain further insight into how ALK contributes to neuroblastoma aggressiveness, we searched for known oncogenes in our previously reported ALK-driven gene signature." (PMID 31937834, 2020). "For example, MAPK inhibition in different types of cancer cells addicted to mutant KRAS or RTKs, such as EGFR (NSCLC), HER2 (breast cancer) or ALK (neuroblastoma), can provoke an increase in the secretion of fibroblast growth factor and interleukin-6." (PMID 33291749, 2020). "Anti-ALK CAR has demonstrated its effectiveness against this neuroblastoma subtype in vitro and in vivo." (PMID 33322408, 2020). "Our findings thus point towards a MAPK pathway-dependent ALK-driven regulation of ETV5 in neuroblastoma." (PMID 31937834, 2020). "ALKA-372-001 phase I Trial showed that Entrectinib has a significant antitumor response in TrkA-positive CRC, ALK-rearranged neuroblastoma, and ROS1-, or ALK-positive NSCLC patients." (PMID 31936239, 2020). "Anaplastic lymphoma kinase (ALK) is one of the most promising targets for treatment of neuroblastoma." (PMID 32240155, 2020). "An example in a solid tumor that illustrates the need for high-level antigen expression on the targeted tumor cells is the anaplastic lymphoma kinase (ALK), which is overexpressed on the cell surface in neuroblastoma." (PMID 32357417, 2020). "Most strikingly, such peptides were able to induce specific CTL activity, causing specific lysis of HLA-A-matched ALK-positive ALCL cells, and neuroblastoma cells in vitro." (PMID 32059449, 2020). "In neuroblastoma, the constitutive activation of ALK, and subsequent downstream pathways, have been shown to be involved in cell proliferation, inducing replication stress, migration, and invasion." (PMID 32309213, 2020). "Ribociclib combined with the ALK inhibitor ceritinib showed excellent therapeutic effects in ALK mutant neuroblastoma." (PMID 32357912, 2020).